TNFSF12 (TNF superfamily member 12)
Description:
Binds to FN14 and possibly also to TNRFSF12/APO3. Weak inducer of apoptosis in some cell types. Mediates NF-kappa-B activation. Promotes angiogenesis and the proliferation of endothelial cells. Also involved in induction of inflammatory cytokines. Promotes IL8 secretion.
Synonyms: TWEAK; APO3L; DR3LG; TNF12; TNLG4A
Tractability: Antibody: a drug acting on it is in phase 2 or 3 trials; UniProt places it where antibodies can reach, with high confidence; its Gene Ontology location is reachable by antibodies, with high confidence; UniProt predicts a signal peptide or a membrane-spanning region.
Target class: Secreted protein
Gene: Protein-coding gene on chromosome 17 (7,548,508 to 7,557,890, forward strand). Ensembl gene ENSG00000239697.
Subcellular location: Cell membrane; Secreted (Tumor necrosis factor ligand superfamily member 12, secreted form); Cell membrane (Isoform TWE-PRIL)
Subcellular location (Human Protein Atlas): Vesicles; Predicted to be secreted
Pathways (Reactome):
Immune System: TNF receptor superfamily (TNFSF) members mediating non-canonical NF-kB pathway; TNFR2 non-canonical NF-kB pathway
Gene Ontology:
Molecular function: protein binding; cytokine activity; signaling receptor binding; tumor necrosis factor receptor binding
Biological process: positive regulation of extrinsic apoptotic signaling pathway; positive regulation of protein catabolic process; apoptotic process; endothelial cell migration; extrinsic apoptotic signaling pathway; immune response; positive regulation of angiogenesis; positive regulation of endothelial cell proliferation; signal transduction
Cellular component: perinuclear region of cytoplasm; extracellular region; plasma membrane; membrane
Genetic constraint (gnomAD): Loss-of-function variants: 16 observed, 25.03 expected, observed/expected ratio (o/e) 0.64, 90% interval 0.43 to 0.97. The upper end of that interval is the gene's LOEUF score, 0.97, which puts it in group 4 of 6, group 1 being the genes least tolerant of losing a copy. Missense variants: 324 observed, 292.86 expected, observed/expected ratio (o/e) 1.11, 90% interval 1.01 to 1.21. Synonymous variants: 150 observed, 127.86 expected, observed/expected ratio (o/e) 1.17, 90% interval 1.03 to 1.34.
Gene-disease validity (ClinGen):
ClinGen rates the evidence that TNFSF12 causes each of these diseases.
common variable immunodeficiency (autosomal dominant): Limited.
Homologues: Orthologues: chimpanzee TNFSF12 (100% identical), pig TNFSF12 (91% identical), dog TNFSF12 (90% identical), mouse Tnfsf12 (89% identical), rabbit TNFSF12 (89% identical), guinea pig TNFSF12 (84% identical), macaque TNFSF12 (84% identical), rat Tnfsf12 (63% identical), tropical clawed frog tnfsf12 (45% identical). Paralogues in human: TNFSF13B (15% identical), TNFSF13 (11% identical).
Diseases named in the same sentence as TNFSF12 in open-access papers:
TNFSF12 is named in the same sentence as 209 diseases in open-access papers, as found by Europe PMC text mining. Sharing a sentence is not in itself a finding about the gene and the disease. The quoted sentences say what the papers report.
rheumatoid arthritis (24 papers, 2011 to 2025). A chronic, systemic autoimmune disorder characterized by inflammation in the synovial membranes and articular surfaces. "BIIB023, a humanized anti-TNFSF12 monoclonal IgG1 antibody, is currently in clinical trials for rheumatoid arthritis and has a favorable safety and tolerability profile." (PMID 38443977, 2024). "Persistent TNFSF12-TNFRSF12A signaling has been implicated in the pathogenesis of numerous diseases, including atherosclerosis, ischemic stroke, rheumatoid arthritis (RA), and inflammatory bowel diseases." (PMID 39232561, 2024). "The positive correlation between the expression level of TNFSF12 and rheumatoid arthritis (RA) or hypertension indicated the possible extension of TNFSF12 indications." (PMID 38659056, 2024).
glioma (22 papers, 2013 to 2024). A benign or malignant brain and spinal cord tumor that arises from glial cells (astrocytes, oligodendrocytes, ependymal cells). "TNFSF12 preferentially activates non-canonical NF-κB and promotes the invasive properties of glioma cells." (PMID 32878880, 2020). "Accordingly, TNFSF12 expression has a negative implication to the overall survival of patients with gliomas." (PMID 32878880, 2020).
autoimmune disease (21 papers, 2011 to 2024). A disorder resulting from loss of function or tissue destruction of an organ or multiple organs, arising from humoral or cellular immune responses of the individual to their own tissue constituents. "Among them, TNFSF12, also called TWEAK, has been researched in tumors, autoimmune disease, and inflammatory diseases." (PMID 38443977, 2024).
lupus nephritis (20 papers, 2009 to 2026). Glomerulonephritis in the context of systemic lupus erythematosus. "Increased protein expression of TNFSF12/TWEAK is detected in the renal cortex of patients with lupus nephritis (LN) and treatment of mesangial cells with TNFSF12/TWEAK promotes macrophage chemotaxis, probably through the chemotactic factors that TNFSF12/TWEAK induces." (PMID 35806457, 2022).
atherosclerosis (18 papers, 2013 to 2024). A disease characterized by the build-up of fatty material and calcium deposition in the arterial wall resulting in partial or complete occlusion of the arterial lumen. "Genetic inactivation of Tnfsf12 reduced atherosclerosis extension and severity in diabetic ApoE deficient mice." (PMID 28447667, 2017). "To investigate the role of TWEAK/Fn14 axis on diabetic-accelerated atherosclerosis, we studied the development of atherosclerotic plaques in Tnfsf12+/+ApoE−/−, Tnfsf12−/−ApoE−/−, and anti-TWEAK- or IgG-treated ApoE−/− in streptozotocin-induced diabetic ApoE deficient mice." (PMID 28447667, 2017). "Using two different approaches, genetic deletion of TNFSF12 and treatment with a TWEAK blocking mAb in atherosclerosis-prone mice, we have analysed the effect of TWEAK inhibition on atherosclerotic plaques progression and stability." (PMID 24479820, 2014).
COVID-19 (17 papers, 2020 to 2025). A disease caused by infection with severe acute respiratory syndrome coronavirus 2. "Our analysis revealed that in severe COVID-19 patients, alveolar macrophages communicate with fibroblasts primarily through the TNFSF12-TNFRSF12A pathway." (PMID 39075394, 2024). "In line with this, in patients with severe COVID-19, alveolar macrophages primarily interact with fibroblasts via the TNFSF12-TNFRSF12A signaling pathway, which drives fibroblast proliferation and the production of fibrotic factors." (PMID 39767799, 2024). "Based on the bioinformatics analysis presented above, we propose that alveolar macrophages communicate with fibroblasts via the TNFSF12-TNFRSF12A signaling pathway, thus promoting pulmonary fibrosis in severe COVID-19 patients." (PMID 39075394, 2024). "It further clarifies the communication between Alveolar Macrophages and Fibroblasts through the TNFSF12-TNFRSF12A pathway, ultimately promoting pulmonary fibrosis in severe COVID-19 patients." (PMID 39075394, 2024). "The TNFSF12-TNFRSF12A pathway plays a central role in alveolar macrophage-fibroblast communication and contributes to pulmonary fibrosis in severe COVID-19 patients." (PMID 39075394, 2024). "In summary, our research elucidates for the first time the crucial mechanism of 'communication' between alveolar macrophages and fibroblasts via the TNFSF12-TNFRSF12A pathway, emphasizing its central role in pulmonary fibrosis in severe COVID-19 patients." (PMID 39075394, 2024). "Literature-based data mining and construction of the molecular pathways revealed a total of seven genes connecting ADHD with COVID-19, including CRP, PON1, AR, OXT, IL6, TNFSF12, and IL10.." (PMID 38066446, 2023). "In this study, we aimed to investigate the role of the TNFSF12-TNFRSF12A pathway in mediating communication between alveolar macrophages and fibroblasts, and its implications for the development of pulmonary fibrosis in severe COVID-19 patients." (PMID 39075394, 2024). "Pathway analysis identified several immunity-related genes that may link ADHD to COVID-19, including CRP, OXT, IL6, PON1, AR, TNFSF12, and IL10." (PMID 38066446, 2023). "There were no signal inflows unique to either moderate or severe COVID-19 alone, whereas inflow through TNFRSF12A (due to TNFSF12) and ITGAX and ITGB2 (due to C3) drive outflows in only healthy controls." (PMID 39187683, 2024).
psoriasis (15 papers, 2012 to 2026). An autoimmune condition characterized by red, well-delineated plaques with silvery scales that are usually on the extensor surfaces and scalp. "Currently approved ustekinumab targeting TNFSF12 is mainly used in the treatment of inflammatory diseases such as psoriasis, Crohn’s disease, and ulcerative colitis." (PMID 38977622, 2025). "qPCR results revealed significantly increased expression of Lcn2, Tnfsf12, Il1b, Krt5, and Krt10 mRNA in the skin of Fn14–/– mice with IMQ-induced psoriasis." (PMID 40369189, 2025).
ischemic stroke (13 papers, 2012 to 2025). A stroke disorder caused by obstruction of blood flow to the brain, due to thrombotic (local blood clot formation) or embolic (due to a blood clot or other material traveling from another site) event. "We also demonstrated that TNFSF12 reduces the risk of CES, whereas previous studies suggested that TNFSF12 can cause ischemic strokes." (PMID 38977622, 2025). "MR analysis of drug targets for ischemic stroke revealed that TNFSF12 could promote SAH and ICH via the use of pQTLs to analyze blood proteins, and we obtained similar results using different IVs." (PMID 38977622, 2025). "To explore the potential side effects of these targets, we analyzed whether druggable genes influence ischemic stroke and found that TNFSF12, SLC22A4, and SPARC influence the occurrence of certain ischemic stroke subtypes." (PMID 38977622, 2025).
Stroke (11 papers, 2012 to 2025). Sudden impairment of blood flow to a part of the brain due to occlusion or rupture of an artery to the brain. "Eight protein-disease pairs were ranked as the most valuable findings after the filtering, which include IL-7R and TNFSF12 level on asthma; ACE level on COPD; AIF1 level on HF; SERPINF1 level on stroke; and SERPINE2, F11, KLKB1, and ABO level on VTE." (PMID 36388766, 2022). "The negative correlation between the serum TNFSF12 level and circulatory system diseases such as atrial fibrillation and stroke suggested the probable side effects of TNFSF12 inhibitors, which deserved extra attention in circulatory disorders." (PMID 38659056, 2024).
glioblastoma (10 papers, 2013 to 2023). The most malignant astrocytic tumor (WHO grade IV). "Since no study of TNF-TNFRSF1A and TNFSF12-TNFRSF12A has been reported so far, our study discovered novel glioblastoma-macrophage/microglia interactive patterns." (PMID 36494582, 2023).
Obesity (9 papers, 2013 to 2025). Accumulation of substantial excess body fat. "MVMR further revealed that CXCL9, TNFSF12 (all-grade), and CCL25 (high-grade) exert BMI-independent effects, implicating direct immunomodulatory pathways rather than obesity-related inflammation." (PMID 40722787, 2025).
pancreatic cancer (8 papers, 2018 to 2025). "RG7212, a fully humanized IgG1κ monoclonal antibody that attenuates the binding of Fn14 to TNFSF12, has been shown to inhibit tumor growth in multiple in vivo models, including renal, breast, and pancreatic cancers." (PMID 38443977, 2024).
Cerebral ischemia (7 papers, 2012 to 2025). Restriction of arterial blood supply to the brain associated with insufficient oxygenation to support the metabolic requirements of the tissue. "This subpopulation received extensive signals from microglia and monocyte subpopulations through the TNF receptor super family member TWEAK/TNFSF12, which has previously been reported to mediate neuronal death in cerebral ischemia." (PMID 40450318, 2025).
diabetes (7 papers, 2012 to 2026). "After 10 weeks of diabetes induction, ≈40% plaques in Tnfsf12+/+ApoE−/− were advanced plaques (grade IV) while only ≈10% plaques were early lesions (grade I)." (PMID 28447667, 2017).
breast carcinoma (6 papers, 2013 to 2023). "In the current study, we found that TNFSF12 acts as a protective factor in breast cancer and that poor survival of breast cancer patients was related to decreased expression of TNFSF12." (PMID 35602610, 2022). "All these indicate that further studies are needed to elucidate the specific role and mechanism of TNFSF12 in breast cancer." (PMID 35602610, 2022). "Meanwhile, previous studies also indicated that TNFSF12 might play a pro-tumorigenic role in human breast cancer." (PMID 35602610, 2022). "These included urokinase plasminogen activator (PLAU) a well characterized prognostic and predictive marker for breast cancer invasion, the cell adhesion metallopeptidase ADAM8, implicated in tumor-progressive degradation of ECM proteins, and a pro-inflammatory cytokine, TNFSF12." (PMID 24498382, 2014). "TNFSF12, TNNI3, SCG2, and COL4A3 were identified as prognostic biomarkers in breast cancer by univariate and multivariate Cox regression algorithms." (PMID 35602610, 2022).
heart failure (6 papers, 2008 to 2023). Inability of the heart to pump blood at an adequate rate to meet tissue metabolic requirements. "Findings from GWAS and Mendelian randomization-proteomics identify seven (CAMK2D, PRKD1, PRKD3, MAPK3, TNFSF12, APOC3 and NAE1) proteins as potential targets for interventions to be used in primary prevention of heart failure." (PMID 37429843, 2023).
Hypertension (5 papers, 2014 to 2025). The presence of chronic increased pressure in the systemic arterial system. "Our study also proved that TNFSF12 can cause the effect of hypertension, while hypertension is a clear risk factor for IA, so we can assume that hypertension is an important mediator." (PMID 38977622, 2025). "A cis-pQTL for TNFSF12 (TWEAK) was associated with risk of hypertension." (PMID 37563310, 2023). "Our study provides strong evidence that TNFSF12, SLC22A4, and SPARC may be potential risk factors for hemorrhagic stroke and that their induction of hypertension may be involved in potential pathogenesis." (PMID 38977622, 2025). "TNFSF12 promoted IA and SAH, SLC22A4 increased the risk of IA rupture leading to SAH, and SPARC was a risk factor for ICH, for which hypertension may be a potential mediator." (PMID 38977622, 2025). "Examples of genetically anchored protein–disease connections included: TNFSF11 (RANKL) with osteoporosis and hypothyroidism, NGF (nerve growth factor) with migraine, TNFSF12 (TWEAK) with hypertension and fibroblast growth factor 5 (FGF5) with hypertension and cardiovascular diseases." (PMID 37563310, 2023).
lung carcinoma (4 papers, 2014 to 2022). "Compared with the control, cells exposed to recombinant protein TNFSF12 exhibited significantly enhanced migration and invasion ability but a slightly reduced proliferation of lung cancer cells." (PMID 34676217, 2021). "It is known that VEGF is an NFκB-inducible protein and is one of the most potent angiogenic factors crucial for tumor metastasis, and qRT-PCR analysis showed that VEGFA expression was remarkably upregulated in lung cancer cells with recombinant protein TNFSF12 treatment at 48 h." (PMID 34676217, 2021).
periodontitis (4 papers, 2011 to 2025). An acute or chronic inflammatory process that affects the tissues that surround and support the teeth. "The results provided genetic evidence for significant associations between genetically predicted levels of family Pasteurellaceae, 45 blood metabolites, and 4 inflammatory proteins (IL-4, IL-22RA1, S100-A12, TNFSF12) and periodontitis susceptibility." (PMID 41001956, 2025). "Our data showed that several inflammatory mediators were increased in RA-periodontitis saliva as compared to non-RA, including TWEAK/TNFSF12, pentraxin-3, IL-19, IL-35, gp130/sIL6Rb, sIL-6Ra, IFN-α2 and sTNF-R1." (PMID 35360114, 2022). "Among the detected inflammatory mediators in saliva samples, TWEAK/TNFSF12, IL-35, IFN-α2, pentraxin-3, gp130/sIL6Rb, sIL-6Ra, IL-19 and sTNF-R1 were found to be significantly increased in patients with periodontitis and RA compared to non-RA group with periodontitis." (PMID 35360114, 2022).
atrial fibrillation (3 papers, 2018 to 2024). A disorder characterized by an electrocardiographic finding of a supraventricular arrhythmia characterized by the replacement of consistent P waves by rapid oscillations or fibrillatory waves that vary in size, shape and timing and are accompanied by an irregular ventricular response. "Three out of the four proteins (DUSP13, TNFSF12 and IL6R) had a drug prioritizing score for atrial fibrillation of 0.26, 0.38 and 0.88, respectively (values closer to 1 indicating stronger evidence of the protein as a potential drug target)." (PMID 35292824, 2022).
cardiac hypertrophy (3 papers, 2014 to 2023). "One of the regulatory molecular pathways in charge of the mediation of cardiac hypertrophy is the tumor necrosis factor receptor superfamily member (TNFSF12)/ tumor necrosis factor receptor superfamily member 12a (TNFRSF12a) system." (PMID 37691190, 2023). "In addition, the role of TNFSF12/TNFRSF12a as a positive regulatory factor in cardiac hypertrophy was verified in the experimental model of right ventricular hypertrophy." (PMID 37691190, 2023).
colon cancer (3 papers, 2017 to 2022). "The TNFRSF18 and TNFSF12 genes are related to tumor necrosis factor (TNF), which is a well-known inflammatory biomarker that promotes cytokines in colon cancer." (PMID 33670198, 2021).
dilated cardiomyopathy (3 papers, 2013 to 2023). Cardiomyopathy which is characterized by dilation and contractile dysfunction of the left and right ventricles. "Transgenic mice and adenoviral-mediated gene expression models have also pointed to the role of TNFSF12 in the development of dilated cardiomyopathy and severe cardiac dysfunction." (PMID 37429843, 2023).
multiple myeloma (3 papers, 2011 to 2022). "The tumor necrosis factor ligand superfamily member 13 or APRIL (TNFSF13) and TNFSF12-TNFSF13 were significantly upregulated in EV from MGUS patients when compared to myeloma patient EV." (PMID 35800053, 2022).
muscle atrophy (3 papers, 2024 to 2025). The loss of muscle tissue due to inactivity or disease. "Studies have shown that TNFSF12 and its associated factor, fibroblast growth factor-inducible type 14 (Fn14), is an emerging apoptosis inducer to play an important role in the pathogenesis of muscle atrophy, which has also been validated in mouse models and clinical cohorts." (PMID 38443977, 2024).
pulmonary fibrosis (3 papers, 2013 to 2024). Chronic progressive interstitial lung disorder characterized by the replacement of the lung tissue by connective tissue, leading to progressive dyspnea, respiratory failure, or right heart failure. "Previous studies have demonstrated an association between the TNFSF12-TNFRSF12A pathway and pulmonary fibrosis, indicating its significant role in the development and progression of the disease." (PMID 39075394, 2024). "This study highlights the crucial role of communication between alveolar macrophages and fibroblasts via the TNFSF12-TNFRSF12A pathway in the development of pulmonary fibrosis." (PMID 39075394, 2024). "This specific interaction is mediated via the TNFSF12-TNFRSF12A pathway and is regarded as a crucial mechanism in promoting pulmonary fibrosis." (PMID 39075394, 2024). "Recent studies have indicated that alveolar macrophages establish communication with fibroblasts through the TNFSF12-TNFRSF12A pathway, which may potentially expedite the progression of pulmonary fibrosis." (PMID 39075394, 2024). "Based on these two pieces of information, it can be inferred that the TNFSF12-TNFRSF12A pathway may play a crucial role in influencing fibroblast behavior and promoting the progression of pulmonary fibrosis." (PMID 39075394, 2024).